Y_RNA (Y RNA )
Gene: Miscellaneous RNA gene on chromosome X (55,582,733 to 55,582,834, forward strand). Ensembl gene ENSG00000200635.
Homologues: Orthologues: chimpanzee Y_RNA (100% identical). Paralogues in human: Y_RNA (89% identical), RNY3 (88% identical), RNY3P1 (87% identical), Y_RNA (87% identical), Y_RNA (86% identical), RNY3P11 (85% identical), Y_RNA (85% identical), Y_RNA (84% identical), Y_RNA (83% identical), RNY3P14 (82% identical), Y_RNA (82% identical), Y_RNA (81% identical), and 96 more.